GPATCH1 (G-patch domain containing 1)
Synonyms: ECGP; GPATC1; FLJ10206; FLJ38686
Tractability: PROTAC: UniProt records ubiquitination sites on it; ubiquitination databases record sites on it; its protein half-life has been measured.
Gene: Protein-coding gene on chromosome 19 (33,080,899 to 33,130,954, forward strand). Ensembl gene ENSG00000076650.
Subcellular location (Human Protein Atlas): Nucleoplasm; Cytosol; Primary cilium
Pathways (Reactome):
Metabolism of RNA: mRNA Splicing - Major Pathway
Gene Ontology:
Molecular function: nucleic acid binding
Biological process: mRNA splicing, via spliceosome; mRNA processing
Cellular component: catalytic step 2 spliceosome; nucleoplasm
Genetic constraint (gnomAD): Loss-of-function variants: 41 observed, 73.78 expected, observed/expected ratio (o/e) 0.56, 90% interval 0.43 to 0.72. The upper end of that interval is the gene's LOEUF score, 0.72, which puts it in group 2 of 6, group 1 being the genes least tolerant of losing a copy. Missense variants: 823 observed, 930.31 expected, observed/expected ratio (o/e) 0.88, 90% interval 0.83 to 0.94. Synonymous variants: 310 observed, 353.71 expected, observed/expected ratio (o/e) 0.88, 90% interval 0.8 to 0.96.
Homologues: Orthologues: chimpanzee GPATCH1 (99% identical), dog GPATCH1 (90% identical), macaque GPATCH1 (89% identical), pig GPATCH1 (88% identical), rabbit GPATCH1 (87% identical), mouse Gpatch1 (84% identical), rat Gpatch1 (84% identical), guinea pig GPATCH1 (83% identical), tropical clawed frog gpatch1 (57% identical), zebrafish gpatch1 (52% identical), Drosophila melanogaster CG8833 (31% identical), Caenorhabditis elegans gpch-1 (26% identical).
Diseases named in the same sentence as GPATCH1 in open-access papers:
GPATCH1 is named in the same sentence as 7 diseases in open-access papers, as found by Europe PMC text mining. Sharing a sentence is not in itself a finding about the gene and the disease. The quoted sentences say what the papers report.
influenza (1 paper, 2020). An acute viral infection of the respiratory tract, occurring in isolated cases, in epidemics, or in pandemics; it is caused by serologically different strains of viruses (influenzaviruses) designated A, B, and C, has a 3-day incubation period, and usually lasts for 3 to 10 days. "Among those, two GPATCH1 polymorphisms (rs2287679 and rs10416265), consistently influenced cytokine production induced by influenza, suggesting a new biological role for GPATCH1 in antiviral immunity." (PMID 32999407, 2020).
osteoporosis (1 paper, 2021). A condition of reduced bone mass, with decreased cortical thickness and a decrease in the number and size of the trabeculae of cancellous bone (but normal chemical composition), resulting in increased fracture incidence. "Although the G-patch domain containing 1 gene (GPATCH1), identified as BMD candidate, is considered a candidate gene for osteoporosis in humans, functional information is limited and its role in skeletal pathophysiology is not yet clear." (PMID 34066823, 2021).
GPATCH1 also shares sentences with these, for which no sentence is quoted: cleft lip (1 paper); colon cancer (1); colorectal cancer (1); keloid (1); rectal cancer (1).